RN7SKP265 (RN7SK pseudogene 265)
Gene: Miscellaneous RNA gene on chromosome 3 (181,968,459 to 181,968,681, forward strand). Ensembl gene ENSG00000252257.
Homologues: Orthologues: chimpanzee 7SK (99% identical), mouse Gm54993 (51% identical). Paralogues in human: RN7SKP187 (63% identical), RN7SKP243 (62% identical), RN7SKP62 (62% identical), RN7SKP81 (61% identical), RN7SKP193 (61% identical), RN7SKP206 (61% identical), RN7SKP217 (61% identical), RN7SKP222 (61% identical), RN7SKP269 (61% identical), RN7SKP284 (61% identical), RN7SKP50 (61% identical), RN7SKP176 (61% identical), and 284 more.